PHGDH (phosphoglycerate dehydrogenase)
Diseases named in the same sentence as PHGDH in open-access papers (continued):
Sharing a sentence is not in itself a finding about the gene and the disease.
glioblastoma (13 papers, 2013 to 2026). The most malignant astrocytic tumor (WHO grade IV). "For instance, in glioblastoma, PHGDH supports hypoxia tolerance by maintaining NADPH levels and redox homeostasis, mitigating ROS-induced death." (PMID 41486146, 2026). "Oxygen deprivation upregulates PHGDH expression in glioblastoma, while ERN1 knockdown enhances this hypoxic induction by releasing repression." (PMID 41486146, 2026). "In one study, it was found that PHGDH-mediated endothelial cell metabolism contributes to glioblastoma resistance to chimeric antigen receptor-T-cell immunotherapy." (PMID 38945960, 2024). "Independently, the TME cues ATF4 transcription of phosphoglycerate de-hydrogenase (PHGDH) in endothelial cells triggering altered metabolism towards glycolysis and aberrant over-sprouting vascularization in glioblastoma." (PMID 37601686, 2023). "It was also demonstrated that PHGDH-mediated endothelial cell (EC) metabolism promotes hypoxia and immunosuppression in the tumor microenvironment, leading to glioblastoma (GBM) resistance to chimeric antigen receptor T-cell (CAR-T) cellular immunotherapy." (PMID 38111705, 2023). "Additionally, PHGDH blockade enhances immunotherapeutic efficacy; in glioblastoma, it normalizes pathological vasculature to potentiate CAR-T infiltration and cytotoxicity." (PMID 41486146, 2026). "Similarly, PHGDH sustains cancer stemness in glioblastoma and AML, while its ablation triggers differentiation in NSCLC." (PMID 41486146, 2026). "After establishing that PHGDH drives glioblastoma’s jungle-like vasculature and suppressive T-cell immunity, Zhang and colleagues demonstrated that PHGDH inhibition sensitized glioblastoma to CAR T-cell therapy and substantially increased survival in mouse models." (PMID 38132354, 2023). "PHGDH inhibition may thus suppress proliferation of glioblastoma, but identifying patients likely to respond to PHGDH inhibition may be important because our results showed that PHGDH was unaffected in glioblastoma compared to near-normal brain." (PMID 36175487, 2022). "Our results showed that SHMT2 and PSPH were upregulated in SSP, while their upstream enzymes PSAT1 or PHGDH were downregulated or unaffected in glioblastoma, suggesting that the SSP in glioblastoma might be independent of carbon flux from glycolysis." (PMID 36175487, 2022). "U251 human glioblastoma cells were selected as a model cell system to mimic a heterozygous condition because of the documented endogenous expressions of the PP enzymes (15.28 ± 1.91, 3.06 ± 0.38 and 3.63 ± 1.34 ng per 105 cells for PHGDH, PSAT and PSP, respectively)." (PMID 40679944, 2025). "In glioblastoma stem-like cells (GSCs), it activates PHGDH to confer radioresistance via redox modulation, while wild-type IDH1 stabilizes PHGDH to preserve NSCLC stemness." (PMID 41486146, 2026). "To understand the relationship between PHGDH and the stemness of CSLCs, we compared the levels of PHGDH in primary, patient-derived CD133+ glioblastoma (GBM) cells." (PMID 30250195, 2018).
ovarian carcinoma (13 papers, 2016 to 2026). A malignant neoplasm originating from the surface ovarian epithelium. "As recently demonstrated, a strong association between relapse of disease in a cohort of ovarian cancer patients receiving Cisplatinum and, at the same time, having a low level of PHGDH, was well-documented." (PMID 37376060, 2023). "In our recent study, we reported that PHGDH is upregulated at translational level and implicated in platin-resistant in epithelial ovarian cancer cells." (PMID 36105480, 2022). "Here, the authors show that downregulation of the serine biosynthesis enzyme PHGDH in a fraction of patients is associated with relapse in platinum-treated ovarian cancers and to NAD+ and PARP activity upregulation." (PMID 35931688, 2022). "The current study demonstrated that PHGDH, the key enzyme implicated in serine biosynthesis pathway, was upregulated in cisplatin-resistant ovarian cancer cells and tissues." (PMID 34178629, 2021). "The promotive role of PHGDH in cisplatin-resistant, invasion and spheroid formation of ovarian cancer cells promoted us to further investigate the underlying mechanisms of its upregulation in platin-resistant ovarian cancer." (PMID 34178629, 2021). "Studies have also shown that PHGDH expression is increased in platinum-resistant ovarian cancer cells and tissues." (PMID 38945960, 2024). "The overexpression of PHGDH increased the survival rate of ovarian cancer cells upon exposure to cisplatin and increased their invasiveness and spheroid formation ability." (PMID 38945960, 2024). "Meanwhile, overexpression of LncRNA RMRP or DDX3X can promote cisplatin resistance and spheroid formation in platinum-resistant ovarian cancer by increasing the translation of PHGDH mRNA." (PMID 37127605, 2023). "A high level of PHGDH relates to resistance to cisplatin, 5-FU and Sorafenib in ovarian cancer, colorectal cancer and liver cancer, respectively." (PMID 37376060, 2023). "Through our research, we can get a knowledge of the tumor suppressing role of PHGDH inhibitor CBR-5884 in epithelial ovarian cancer via regulating the ROS level and the downstream Wnt/β-catenin signaling pathway." (PMID 36105480, 2022). "To investigate serine biosynthetic activity in platinum-resistant ovarian cancers, we assessed gene expression levels of PHGDH (mRNA) in the original HGSC dataset from TCGA27, with n = 287 newly diagnosed cases reporting platinum status." (PMID 35931688, 2022). "In conclusion, our study demonstrated that PHGDH inhibitor CBR-5884 inhibits epithelial ovarian cancer proliferation, migration, and invasion through activating ROS/Wnt/β-catenin pathway and plays a synergistic role with PARP inhibitor olaparib." (PMID 36105480, 2022). "In our recent study, we found that PHGDH was upregulated in epithelial ovarian cancer and was regulated by lncRNA RMRP and DDX3X in translational level." (PMID 36105480, 2022). "Based on the expression of PHGDH expression, patients with ovarian cancer were grouped into high and low expression groups." (PMID 34178629, 2021). "The current study demonstrated that PHGDH is upregulated in platin-resistant ovarian cancer cells and tissues at the protein level." (PMID 34178629, 2021). "In conclusion, the current study demonstrates that PHGDH is upregulated and plays a critical role in cisplatin resistance in ovarian cancer cells." (PMID 34178629, 2021). "The current study demonstrated that PHGDH translation was upregulated in platin-resistant ovarian cancer." (PMID 34178629, 2021). "Thereby, our findings identified cooperation of DDX3X and RPRM to promote translation of PHGDH transcript in cisplatin-resistant ovarian cancer cells." (PMID 34178629, 2021). "PHGDH expression was then investigated in a panel of ovarian cancer tissues using immunohistochemical staining." (PMID 34178629, 2021).
ovarian carcinoma (continued). "Our data suggest that PHGDH translational efficiency is different in platin-resistant and platin-sensitive ovarian cancer cells, which further adds diversity to the regulation of PHGDH expression in the distinct cancers." (PMID 34178629, 2021). "PHGDH expression was apparently recovered after 1 h free of CHX in SKOV3/DDP and A2780/DDP cells, while its expression was delayed in their parental partners, confirming that PHGDH translation is activated in platin-resistant ovarian cancer cells." (PMID 34178629, 2021). "PHGDH expression was also further investigated in 16 platin-sensitive and eight platin-resistant ovarian cancer tissues." (PMID 34178629, 2021). "PHGDH expression was higher in most of platin-resistant ovarian cancer tissues than in platin-sensitive tissues." (PMID 34178629, 2021). "Kaplan–Meier survival analysis demonstrated that high PHGDH predicted significantly poor overall survival of patients with ovarian cancer." (PMID 34178629, 2021). "The current study found that although total DDX3X expression was not distinct between cisplatin-sensitive and cisplatin-resistant ovarian cancer cells, while its recruitment on PHGDH mRNA was augmented in cisplatin-resistant ovarian cancer cells." (PMID 34178629, 2021). "We show that high PHGDH expression is correlated with lower overall survival of patients with ovarian cancer." (PMID 34178629, 2021). "In other words, increased PHGDH expression confers resistance to cisplatin on ovarian cancer cells." (PMID 38945960, 2024). "Therefore, the regulation of serine metabolism by RMRP / DDX3X /PHGDH signaling pathway is a potential therapeutic target for platinum-resistant ovarian cancer." (PMID 37127605, 2023). "Analyzing matched samples collected longitudinally during disease course, we found that a subgroup of ovarian cancer patients relapsed after platinum-based chemotherapy are characterized by decreased intratumor PHGDH levels, and that the extent of such decrease correlates with worse prognosis." (PMID 35931688, 2022). "Thus, we investigated the function and possible mechanism of PHGDH inhibitor CBR-5884 on epithelial ovarian cancer in vitro and in vivo." (PMID 36105480, 2022). "qRT-PCR found that no obvious alteration of PHGDH mRNA was observed in platin-resistant SKOV3 and A2780 cells when compared with their platin-sensitive partners, indicating that PHGDH was upregulated in platin-resistant ovarian cancer cells at the protein level." (PMID 34178629, 2021). "Furthermore, we found that PHGDH knockout inhibited the proliferation of ovarian cancer cells, while PHGDH overexpression increased the survival rate, invasiveness and spheroid formation of ovarian cancer cells after cisplatin exposure." (PMID 34178629, 2021). "Importantly, knockdown of DDX3X significantly decreased PHGDH expression in cisplatin-resistant ovarian cancer cells." (PMID 34178629, 2021). "PHGDH was expressed in 118 of 154 epithelial ovarian cancer specimens." (PMID 34178629, 2021). "In addition, PHGDH increases resistance of ovarian cancer cells to cisplatin and promotes invasiveness and spheroid formation of ovarian cancer, making PHGDH a potential target for ovarian cancer therapy." (PMID 34178629, 2021). "Importantly, knockdown of PHGDH suppressed, while overexpression of PHGDH increased the survival upon cisplatin exposure, invasiveness and spheroid formation of ovarian cancer cells." (PMID 34178629, 2021). "Collectively, the current study described that PHGDH was upregulated and conferred resistance of ovarian cancer cells to cisplatin, suggesting that cisplatin resistance could be overcome by targeting PHGDH." (PMID 34178629, 2021). "Thus, this study suggests that targeting PHGDH may provide a potential opportunity to overcome cisplatin resistance in ovarian cancer." (PMID 34178629, 2021).
ovarian carcinoma (continued). "Therefore, targeting PHGDH might render resistant cells sensitive to cisplatin, providing a potential strategy for treatment of cisplatin resistant ovarian cancer." (PMID 34178629, 2021). "Importantly, high PHGDH expression predicted a poor prognosis of patients with ovarian cancers." (PMID 34178629, 2021). "We show that PHGDH is upregulated at the translational level in cisplatin resistant ovarian cancer cells, which is regulated by recruitment of DDX3X on the PHGDH transcript." (PMID 34178629, 2021). "The current study found that long non-coding RNA (Lnc RNA) RPRM was upregulated in cisplatin-resistant ovarian cancer cells and promoted enrichment of DDX3X on the PHGDH mRNA." (PMID 34178629, 2021). "As case study, we quantified expression of MCT1, MCT4, GLS, PHGDH, FAS, and ACC in 17 patient-derived ovarian cancer xenografts and correlated it with survival." (PMID 32974128, 2020). "However, the role of PHGDH in cell ROS level and its downstream pathways has not been explored in epithelial ovarian cancer." (PMID 36105480, 2022). "Enrichment of PHGDH mRNA by pan-Ago was not significantly different between platin-resistant and platin-sensitive SKOV3 and A2780 cells, indicating that miRISCs might not be implicated in differential translation of PHGDH between platin-resistant and platin-sensitive ovarian cancer cells." (PMID 34178629, 2021). "However, the role of PHGDH inhibitor CBR-5884 in cell ROS level and its downstream pathways has not been explored in epithelial ovarian cancer." (PMID 36105480, 2022). "DDX3X expression was not different, while its enrichment on the PHGDH mRNA was increased, indicating that other factor(s) might guide DDX3X to the PHGDH mRNA in platin-resistant ovarian cancer." (PMID 34178629, 2021).
gastric cancer (12 papers, 2017 to 2026). A primary or metastatic malignant neoplasm involving the stomach. "Elevated PHGDH expression is strongly associated with poor clinical outcomes in patients with gastric cancer." (PMID 41415540, 2025). "Glutamine restriction in gastric cancer triggers ATF4/CEBPB-driven PHGDH upregulation to sustain nucleotide synthesis and redox homeostasis." (PMID 41486146, 2026). "Under glutamine deprivation, gastric cancer cells upregulate PHGDH to sustain mitochondrial folate cycling and NADPH generation, promoting survival." (PMID 41486146, 2026). "In terms of overcoming drug resistance, the interaction of phosphoglycerate dehydrogenase (PHGDH) with IGF2BP1 can facilitate the m6A-dependent stabilization of transcription factor 7 Like 2 (TCF7L2) mRNA to confer multidrug resistance in gastric cancer." (PMID 40986143, 2025). "In gastric cancer, PHGDH is significantly overexpressed in multidrug-resistant cells and facilitates resistance development through activation of the PHGDH/IGF2BP1-TCF7L2 axis." (PMID 41415540, 2025). "Among hit compounds, a commercially available and assessable compound, Chicoric acid, was purchased to evaluate its anti-cancer potential against PHGDH overexpressing gastric cancer cell line MGC-803 and SGC-7901." (PMID 36144843, 2022). "Messenger RNA and protein product PHGDH have been reported to exhibit gastric tissue preferred expression in samples from gastric cancer patients." (PMID 36144843, 2022). "MTT assay analysis of a commercially available compound, Chicoric acid, against gastric cancer cells identified Chicoric acid as a potent anti-cancer agent for the treatment of cancers with overexpression of PHGDH." (PMID 36144843, 2022). "The overexpression of PHGDH has been reported in different cancer cell lines such as lung cancer, glioma, gastric cancer breast cancer, and colon cancer." (PMID 36144843, 2022). "The knockdown of PHGDH in gastric cancer cells (SGC-7901 and MGC-803) leads to an elevated apoptosis percentage, suggesting that these gastric cancer cell lines are sensitive to PHGDH depletion as cancer cells with expression of PHGDH were found to be uniquely sensitive to PHGDH knockdown." (PMID 36144843, 2022). "FAK and PHGDH were reported to be novel prognostic biomarkers in gastric cancer." (PMID 28188704, 2017). "To determine whether PHGDH hypermethylation may also induce serine auxotrophy, we acquired two cell lines–Hec1A (endometrial cancer) and AGS (stomach cancer)–both of which display high PHGDH methylation and low PHGDH mRNA expression in CCLE data." (PMID 35045283, 2022).
leukemia (12 papers, 2014 to 2025). A malignant (clonal) hematologic disorder, involving hematopoietic stem cells and characterized by the presence of primitive or atypical myeloid or lymphoid cells in the bone marrow and the blood. "Our previous study revealed that P2X7 enhance leukemia progress via PHGDH-mediated serine metabolic pathways." (PMID 36418376, 2023). "In leukemia cells, glutamine deprivation upregulates the serine pathway with increased expression of phosphoglycerate dehydrogenase (PHGDH) and phosphoserine aminotransferase (PSAT)." (PMID 33468252, 2021). "Specifically, it was demonstrated that silencing PHGDH has a detrimental effect on leukemia cell growth and survival and PHGDH gene overexpression was among the 4-gene signature reported to be an independent negative prognostic marker in patients with AML." (PMID 33652666, 2021). "Its role is far less well studied in leukemia, but serine deprivation and PHGDH inhibition were reported to cooperate to inhibit growth of the malignant human myeloid cell line HL6054." (PMID 31235852, 2019). "We finally evaluated the effects of various pharmacological inhibitors of Gln metabolism on the proliferation of PHGDH knock-down leukemia cells." (PMID 26625201, 2016). "To further illustrate the critical role of serine in leukemia cells, we examined the combined effects of Gln-starvation and either serine withdrawal or PHGDH siRNA on cell growth." (PMID 26625201, 2016). "We also documented that cell exposure to H2O2 led to PHGDH protein upregulation and further increased the cytotoxic effects of PHGDH silencing in L-ase-treated cells, thereby proving the role of PHGDH in the antioxidant defenses of leukemia cells." (PMID 26625201, 2016). "To understand the role of serine in leukemia cells, we genetically silenced PHGDH and/or used serine-deprived culture medium." (PMID 26625201, 2016). "PHGDH transcriptional expression was identified in several human leukemias (Jurkat, MOLT-3, HL-60, U937, and THP-1), T-cell lymphoblastic lymphoma (Sup-T1), colon adenocarcinoma (COLO 320DM), epithelioid carcinoma (HeLa S3), and murine lymphoma (BW5147.G.1.4)." (PMID 25574168, 2014). "In response to glutamine withdrawal, leukemia cells upregulate PHGDH and PSAT, suggesting that targeting both serine and glutamine metabolism may result in synergistic anti-leukemic activity." (PMID 36578934, 2022). "Finally, we showed that PHGDH silencing in vitro and the use of serine-free diet in vivo inhibited leukemia cell growth, an effect further increased when glutamine metabolism was blocked." (PMID 26625201, 2016). "We found that the inhibitory effects of PHGDH silencing and serine withdrawal on leukemia cell proliferation were additive, if not synergistic, revealing the high dependence of leukemia cells on both endogenous and exogenous serine." (PMID 26625201, 2016). "Silence of the phosphoglycerate dehydrogenase (PHGDH) enzyme involved in the serine biosynthesis pathway is detrimental to the growth and survival of leukemia cells." (PMID 35721208, 2022). "In this study, we identified a reverse correlation between Gln concentration and the expression of two major enzymes of the serine pathway, PHGDH and PSAT in several leukemia cells." (PMID 26625201, 2016). "We further documented in immunoblot experiments that the upregulation of PHGDH and PSAT was inversely proportional to the amount of glutamine in the medium; we obtained similar results in other leukemia cell lines and also when using L-ase." (PMID 26625201, 2016). "Interestingly, since PHGDH inhibitors are not yet available, we fed leukemia-bearing mice with a diet deficient in serine and glycine, and documented that this diet combined with the daily administration of BPTES was sufficient to significantly prolong the life of treated mice." (PMID 26625201, 2016).
leukemia (continued). "We first examined whether HL-60 leukemia cells were sensitive to a reduction in serine concentration by using serine-deprived medium combined or not with PHGDH-targeting siRNA." (PMID 26625201, 2016).